HGF (hepatocyte growth factor)
Diseases named in the same sentence as HGF in open-access papers (continued):
Sharing a sentence is not in itself a finding about the gene and the disease.
tumor (continued). "This in vivo study showed that, in contrast to propofol, sevoflurane exposure resulted in bigger ex vivo tumour size, shorter survival time, higher HGF and HIF1α expression, and lower TIMP-2 expression than propofol injection." (PMID 35953652, 2023). "Further, they illustrated that the VEGF and HGF cooperated to promote tumor angiogenesis, which produced by these types of cancer cells." (PMID 37153782, 2023). "In this study, we evaluated tumor shrinkage as the indicator of cabozantinib treatment response and the correlation of baseline HGF levels." (PMID 36595123, 2023). "The function of HGF as a stromal cell-derived factor influences cancer cell invasiveness within the tumor microenvironment." (PMID 37835402, 2023). "HGF contributes to desmoplasia as well as to the acidification of the TME through the regulation of tumor metabolism." (PMID 36980785, 2023). "HGF secretion is predominantly attributed to stromal cells, but tumor-derived HGF has also been reported in EGFR TKI-resistant tumor cells." (PMID 36647832, 2023). "Human hepatocyte growth factor tricyclic fragment (HGFK1) is a domain of HGF, which has the effects of anti-angiogenesis and inhibiting tumor cell invasion and metastasis." (PMID 36094649, 2023). "Aberrant HGF/Met pathway activation can result in increased tumor invasiveness, angiogenesis and metastasis, and is correlated with poor prognosis in many tumor types." (PMID 36672409, 2023). "And to our knowledge, this is a comparably large sampled study which first focuses on HGF expression in both tumor and plasma in SCLC." (PMID 37828456, 2023). "It has been reported that iCAFs are the main subgroup secreting HGF, further promoting the activation of Hh within tumor cells to compensate for the inhibitory effects of Hh inhibitors, ultimately increasing the tumor's drug resistance." (PMID 37919751, 2023). "The aberrant activation of c-Met and dysregulation of the MET/HGF pathway can lead to cancer cell proliferation, tumour growth, and metastasis." (PMID 37514101, 2023). "TSC2‐ EVs were found to enhance VEGF and HGF secretion from recipient fibroblasts, which we have previously shown to be a feature of a tumour‐supporting fibroblast phenotype." (PMID 37337371, 2023). "The high concentration of HGF in the ECM acts on the c-Met receptor of tumor cells, further enhancing the invasive growth of tumors." (PMID 37919751, 2023). "For instance, hepatocyte growth factor (HGF) produced by M2 macrophages has been shown to promote tumor growth, migration, and invasion." (PMID 37576900, 2023). "Originating from HSCs, CAFs play a significant role in fostering tumor-promoting inflammation by secreting elevated levels of IL-6, hepatocyte growth factor (HGF), vascular endothelial growth factor (VEGF), and angiopoietin-1." (PMID 37894413, 2023). "Elevated HGF levels can stimulate the growth and proliferation of CTCs, epithelial cells, fibroblasts, and other stromal cells that promote tumor growth, invasion, metastasis, and angiogenesis." (PMID 38067195, 2023). "It is likely that these inflammatory mediators are involved in the upregulation of HGF in tumors because they are increased in the tumor microenvironment and contribute to a drug-resistant and/or metastatic tumor microenvironment." (PMID 37835402, 2023). "HGF/c-MET activates multiple cell signaling pathways leading to tumor cell proliferation, such as the RAS, PI3K, or Wnt/β-catenin pathway." (PMID 37511344, 2023). "In mice bearing HGF-independent Hs746T xenografts with METex14 skipping/METamp, effective tumor growth inhibition and regression, respectively, were observed at 3 and 6 mg/kg QD." (PMID 36999986, 2023). "They support tumor survival and growth by secreting various growth factors, cytokines, and chemokines, such as interleukins, HGF, and stromal cell-derived factor 1 alpha (SDF-1α)." (PMID 38239394, 2023). "An elevated secretion of HGF was a better indicator of EV‐activated fibroblasts capable of enhanced tumour growth." (PMID 37337371, 2023).
tumor (continued). "TME enhances the tumor survival pathway by secretion of fibroblast growth factor, hepatocyte growth factor, interleukin-6, and transforming growth factor-β." (PMID 37509281, 2023). "CYP1A2 was identified as an antagonist of the hepatocyte growth factor/c-mesenchymal–epithelial transition factor (HGF/MET) signaling pathway, which is associated with tumor progression, survival, and metastasis." (PMID 38067357, 2023). "The dysregulation of hepatocyte growth factor (HGF) receptor c-Met contributes to tumor progression and metastasis." (PMID 37529603, 2023). "Infiltration levels of M2 TAMs and HGF expression were found to be significantly increased in drug-resistant tumor cells compared to sorafenib-sensitive tumors." (PMID 37576900, 2023). "It was also reported that incomplete RFA of a target tumor can sufficiently stimulate residual tumor cells to induce accelerated growth of distant tumors via the IL-6/c-Met/HGF pathway and VEGF production." (PMID 37952066, 2023). "Neoplastic plasma cells produce HGF that is cleaved and activated by uPA and plasmin, leading to IL-11 secretion by osteoblasts and tumor cell invasion mediated by osteoclasts, as uPA inhibition also halts MM invasion." (PMID 37445697, 2023). "HGF plays a crucial role in promoting tumor progression, including the complete LIT-driven one, through the activation of the -MET pathway." (PMID 36831664, 2023). "In murine tumor models where HGF from hepatic stellate cells (HSC)-derived CAFs or MET from tumor cell sources was deleted using Lrat-Cre-transgenic mice, a significant reduction in tumor invasiveness and size was observed." (PMID 37919751, 2023). "A subset of cytokine-producing and quiescent HSCs, on the other hand, carried out a tumor-limiting role by producing protective mediators such as hepatocyte growth factor (HGF)." (PMID 36845555, 2023). "Among them, myofibroblastic CAFs, which produce collagen I, suppress tumor growth by mechanically restraining tumor spread, while inflammatory CAFs which secrete HGF, promote tumor growth." (PMID 38138981, 2023). "Sunitinib can increase the anti-tumor immune response by inhibiting the hepatocyte growth factor (HGF) and vascular endothelial-derived growth factor (VEGF) signaling pathways." (PMID 36672493, 2023). "MET encodes the tyrosine kinase receptor responsible for binding to hepatocyte growth factor (HGF), initiating signaling cascades that drive cell migration, tumor invasion, and metastasis." (PMID 38201232, 2023). "Continuous stimulation with EGF and HGF leads to ligand‐based activation of signalling pathways as is occurring in the tumour." (PMID 37679999, 2023). "HGF/Met signaling also contributes to oncogenesis and tumor progression in many human malignancies, including GBM." (PMID 36672409, 2023). "In turn, activated CAFs can stimulate the HGF/c-MET axis in tumor cells through the secretion of HGF, further enhancing tumor stemness, invasion, and metastasis." (PMID 37919751, 2023). "Various studies demonstrate that CAF-derived hepatocyte growth factor (HGF), the ligand of c-Met, can enhance proliferation and migration of tumor cells in different cancers." (PMID 37566084, 2023). "Western blot analysis showed that the expressions of p-MET and HGF are very low in normal breast tissues but are excessive in tumor tissues of the MDA-MB-231 tumor-bearing nude mice." (PMID 36614199, 2023). "It is noteworthy that many stimuli that trigger MET transcription in cancer cells also lead to HGF upregulation in the tumor stroma, creating a feedforward stimulatory circuit that enhances MET activation." (PMID 38077251, 2023). "In this comprehensive review, we analyze and compare the potential impact of the Hh pathway on the tumor microenvironment (TME) in HGF/c-MET-driven tumor models, as well as the interplay between different cell types." (PMID 37919751, 2023).
tumor (continued). "Dysregulation of the MET/HGF pathway leads to uncontrolled cell proliferation and oncogenesis, and is observed in multiple tumor types." (PMID 37681908, 2023). "The hypoxic environment can also induce the overexpression of the MET proto-oncogene and the activation of c-MET, amplifying the HGF signaling pathway and activating the transcription of hypoxia-inducible genes, ultimately increasing the stemness of the tumor." (PMID 37919751, 2023). "Our previous research demonstrated that HGF treatment reduced the effector capacity of tumor-specific CD8+ T cells in a murine model of CTL-mediated killing." (PMID 38137344, 2023). "The MET/HGF pathway also positively regulates cancer stem cell enrichment and tumour aggressiveness due to stem cell-related resistance to therapy." (PMID 37514101, 2023). "In turn, Spix and coworkers postulated that HGF promotes motility and tumor progression in part by EGFR activation which elevated level is frequently observed in GC; also, this is induced by Hp infection." (PMID 37460910, 2023). "In this study, we showed that HGF, which can be produced by fibroblasts in the tumor microenvironment, induces entrectinib resistance by activating its receptor MET and downstream signaling pathways in NTRK1‐rearranged or ROS1‐rearranged tumor cells." (PMID 36416133, 2023). "As an alternative pathway of VEGF, HGF/c-Met is emerging as a vital role in tumor angiogenesis and resistance to anti-VEGF therapy." (PMID 36959792, 2023). "Among these pathways is the hepatocyte growth factor (HGF)/mesenchymal-epithelial transition factor (MET) signaling cascade, a pro-survival pathway linked to tumor growth, invasion and metastasis." (PMID 35325006, 2022). "The formation of a dense ECM is closely related to the secretion of various factors (collagens I, III, IV, and V, as well as VEGFA, EGF, FGF, HGF, and CXCL12) by tumor-associated fibroblasts in tumor tissue." (PMID 35566065, 2022). "The c-MET/HGF signaling is also known to contribute widely in metabolic reprogramming of tumor cells." (PMID 35081970, 2022). "In general, HGF-induced c-Met signaling and the associated AKT pathway are known to be tumor-promoting factors in terms of cancer cell proliferation, motility, and invasiveness, which corresponds to our findings." (PMID 35454913, 2022). "For what concerns Small-Cell Lung Cancer (SCLC), the activation of HGF/c-MET pathway leads to increased tumor growth and cell survival." (PMID 35069735, 2022). "The possibility exists that MET is highly activated in low expressing tumors, e.g., if there are tumor areas with high levels of HGF in the TME." (PMID 35326642, 2022). "The results showed that the α-SMA, VEGFA and HGF transcriptional levels in the tumor tissue of the ligustilide-treated group were significantly reduced compared to the control group (PBS)." (PMID 35626012, 2022). "Blocking the HGF/c-Met signaling pathway can inhibit the damage of tumor cells to nerves and the vascularization of the tumor in nerves." (PMID 35449152, 2022). "HGF has also been reported to induce the activation of fibroblasts, supporting their tumor-promoting characteristics." (PMID 36010567, 2022). "In vitro analysis revealed that HGF suppresses the anti-tumor effect of lenvatinib on HCC cell lines with high expression levels of c-MET." (PMID 35008398, 2022). "Expression of HGF has been found to be elevated in tumor tissue of patients with NSCLC and especially in patients with tumor recurrence." (PMID 36359256, 2022). "HGF also contributes to local tumor invasion through the focal adhesion kinase (FAK)/paxillin signaling pathways." (PMID 36230676, 2022). "MET and its ligand HGF (hepatocyte growth factor) enhance tumor cells proliferation, invasion, and metastasis in HCC." (PMID 36080304, 2022).
tumor (continued). "We then focused on three genes (CD70, CXCL11, and HGF) which negatively correlated with favorable outcomes to further validate the key factor involved in tumor immune infiltration, especially the correlation with macrophages was mainly focused on." (PMID 35568859, 2022). "The HGF, which can regulate cell growth, cell motility, and morphogenesis in a variety of cell and tissue types, plays an important role in angiogenesis, tumor formation, and tissue regeneration." (PMID 35401705, 2022). "Simultaneously, HGF is always acted as a potent inducer of lymphangiogenesis, angiogenesis, and tumor growth through promoting tumor cell invasion and metastasis." (PMID 35370682, 2022). "Subsequently, MET/HGF-dependent nitric oxide release by neutrophils assists in cancer cell killing, which greatly dampens tumor growth and metastasis." (PMID 35784290, 2022). "HGF released by CAFs stimulates multiple chemicals in the tumor microenvironment, including bFGF, TGF-a, prostaglandin E2 (PGE2), and PDGF, all of which are involved in cancer proliferation, invasion, and metastasis." (PMID 35630066, 2022). "The tumor stroma elevates the expression of proteases such as plasminogen activation system and matriptase that are involved in the activation of pro-HGF." (PMID 35081970, 2022). "HGF is secreted in an inactive proform (pro-HGF) and its activation is mainly due to proteases that are over-expressed in tumor cells." (PMID 35626056, 2022). "It has been shown that aberrant activation of the HGF pathway in tumor tissues can predict drug response." (PMID 35884597, 2022). "The SPINK1 general cancer pathway and HGF signalling were activated in G3 cells in which the tumour malignancy‐related genes RASD1, PIK3R1, JUN, and FOS were significantly upregulated, indicating that G3 promotes malignant progression in GC." (PMID 35184420, 2022). "Hepatocyte growth factor (HGF) mediates multiple important cellular functions involved in tumor growth and development such as differentiation, proliferation, and migration via its receptor c-Met." (PMID 36012373, 2022). "Tumor cells within a 500 μm radius of blood vessels are attracted towards the blood vessels by hepatocyte growth factor (HGF) gradients." (PMID 35565297, 2022). "HGF is a pleiotropic growth factor and cytokine, whose upregulation promotes tumor cell survival, motility, and proliferation, and its receptor, HGFR (a.k.a. c-MET), is a well-known oncogene." (PMID 35366939, 2022). "The hyaluronan synthase 2 myCAFs, but not type I collagen-expressing myCAFs, promoted tumor progression, while HGF-expressing iCAFs enhanced tumor growth via tumor-expressed MET, thereby directly linking CAFs to tumor cells." (PMID 35326670, 2022). "Activation of the HGF/MET signaling pathway driven by a ligand (HGF)-dependent or ligand-independent manner promotes cellular proliferation, angiogenesis, tumor aggressiveness, and invasion, thereby resulting in poor survival outcomes." (PMID 34997350, 2022). "On the other hand, cabozantinib exerts its effect inhibiting proteins involved in regulation of extracellular matrix (ECM) remodelling and tumour invasiveness and motility (SDF1, MMP2 and HGF) by cancer-associated fibroblasts (CAFs)." (PMID 35106125, 2022). "In many tumours, molecules such as hepatocyte growth factor (HGF), epidermal growth factor (EGF), platelet-derived growth factors (PDGF), and TGF-β can act as epithelial-mesenchymal transformation (EMT)-inducible signals." (PMID 36338118, 2022). "Coordination of tumor metabolism and autophagy is also critical for resistance to HGF/MET-targeted therapy." (PMID 36551686, 2022). "Pro-HGF is not a biological precursor because it does not activate MET (mesenchymal-epithelial transition) receptor, known as HGF receptor; however, the activation of two-chain HGF occurs in wounded tissue or the tumor microenvironment." (PMID 35630066, 2022).
tumor (continued). "HGF, which creates a supportive proinvasive microenvironment for the tumor cells, stabilizes this interaction." (PMID 36139568, 2022). "The C-MET/ERK/FRA1/HEY1 axis is mediated by CAF-derived HGF to promote the stemness of tumor-initiating cells." (PMID 36457492, 2022). "The orthotopic liver xenograft tumor model demonstrated that HGF/MET signaling plays a significant role in CD44v6+ HCC cells." (PMID 36387747, 2022). "MET interacts with its ligand hepatocyte growth factor (HGF) and leads to NO-mediated tumor cell killing." (PMID 36555469, 2022). "Researches have demonstrated that c-Met normally mediates downstream signals by combining with its corresponding ligand, hepatocyte growth factor (HGF), to promote the proliferation and differentiation of tumor cells." (PMID 35978812, 2022). "In two pivotal studies published 10 years ago, HGF was shown to mediate resistance to different molecular therapies in tumor cells of different origins." (PMID 36324182, 2022). "Recent reports show that higher serum HGF levels negatively correlate with patient survival time and positively with tumor size." (PMID 36675666, 2022). "Our findings suggest ERα36high CAFs as an additional factor in HGF/c-Met signaling activation and tumor progression in TNBC cells." (PMID 35454913, 2022). "Activated myofibroblasts are a key orchestrating cell population in post RF ablation distant tumor growth, primarily through induction of the HGF/c-MET/STAT3 axis." (PMID 35857766, 2022). "It has been proved that aberrant activation of HGF/c-Met signaling can result in the induction of cell proliferation, invasion, metastasis, tumor angiogenesis and drug resistance of tumor cells in many types of cancers." (PMID 36499211, 2022). "HGF/c-Met signaling is involved in multiple cellular processes, including embryonic development, angiogenesis, and tumor progression in vivo." (PMID 35851277, 2022). "To gain further insight into how HIF1α induces CRC progression, we examined the effect of HIF1α on many microenvironmental genes, including TGF-β, TNF-α, VEGF, EGF, PDGF, b-FGF, HGF, and IGF, which have been implicated in promoting tumor development." (PMID 35355718, 2022). "Stellate cells and myofibroblasts are induced to secrete HGF from tumor cell products, and HGF, in turn, stimulates tumor cell invasiveness." (PMID 36675666, 2022). "Bone marrow-derived suppressive cells infiltrate the primary tumor and induce EMT in tumor cells through the TGF-β, EGF, and HGF signaling pathways, leading to metastasis and the spread of tumor cells." (PMID 36119037, 2022). "The extract specifically decreased serum HGF involved in tumour growth, migration, invasion, and VEGF, essential for tumour angiogenesis." (PMID 35437454, 2022). "The tracer was then administered intravenously to SCID mice xenografts with PC‐9 tumors (HGF− and HGF+) showing liver absorption, a fast renal clearance, and tumor accumulation." (PMID 35292998, 2022). "MET has been found to promote tumour development and metastasis by binding to hepatocyte growth factor (HGF)." (PMID 35711496, 2022). "We also obtained similar results in cultured KGN cells, which are a human granulosa-like tumor cell line, further confirming that HGF increases KITL expression in granulosa cells by binding to c-Met." (PMID 35089464, 2022). "Neuropilin-1 (NRP1) is a transmembrane or cytosolic protein that acts on several signaling pathways, such as angiogenesis through VEGF and HGF in endothelial cells, and is a tumor promotor overexpressed in several tumor tissues." (PMID 35887311, 2022). "U87‐MG xenografts mice were used for in vivo experiments, revealing rapid tumor absorption of 64Cu‐NOTA‐rh‐HGF that was distinctly visible at 30 min postinjection with a peak at 9 h (6.7 ± 1.8% ID/g, percentage injected dose per gram)." (PMID 35292998, 2022).